HMGB1 (high mobility group box 1)
Diseases named in the same sentence as HMGB1 in open-access papers (continued):
Sharing a sentence is not in itself a finding about the gene and the disease.
tumor (continued). "In summary, tumor heterogeneity evaluated by TA was associated with histological heterogeneity in UTUC and represented a HMGB1-mediated inflammatory tumor microenvironment." (PMID 34244567, 2021). "Among them, HMGB1 (High Mobility Group Box 1) is well known as another important ligand for tumor progression." (PMID 34323409, 2021). "We investigated the role of exogenous HMGB1 in tumor proliferation and metastasis using human SW1990 and PANC-1 cells after radiotherapy and explored the possible molecular mechanism." (PMID 34805222, 2021). "In a further step, we demonstrated that HMGB1 secreted by dying tumor cells promoted neosis in a paracrine manner." (PMID 33523579, 2021). "Cumulatively, these results established that targeting HMGB1 (Glycyrrhizin) is proved to be an effective strategy to inhibit ESCC tumor growth, especially for the KDM4Dlow cases." (PMID 34820329, 2021). "Cytosolic translocation of HMGB1 and secretion of HMGB1 by tumor cells in response to chemotherapy are major factors in the disordered tumor microenvironment." (PMID 34778055, 2021). "Recently, it has been reported that several molecules, including calreticulin, HMGB1, and ATP, released by tumor cells are responsible for chemotherapy-induced anticancer immune responses." (PMID 34733785, 2021). "For example, in some studies, HMGB1 has been shown to promote cancer development and chemotherapy resistance; however, in other studies, HMGB1 exhibits tumor-suppressive activities." (PMID 33558529, 2021). "To assess the presence of the prototypic DAMP, associated with high levels of unscheduled cell death and/or cellular stress, within the unique tumor microenvironment of MPEs, we quantified intrapleural HMGB1 using BPEs as a comparator." (PMID 33013860, 2020). "HMGB1 is utilized by tumor cells to divert the potentially protective activities of the innate immune system, specifically those involving activation of TLR4, as well as RAGE, to generate a hyperinflammatory, immunosuppressive, protumorigenic TME." (PMID 32664328, 2020). "We previously performed a proteomic analysis for EVs from GC cells and identified several proteins of interest including HMGB1, which has shown important roles in tumor immune evasion and neutrophil polarization." (PMID 32477934, 2020). "Mechanistically, circFOXM1 functions as a competitive endogenous RNA (ceRNA) for miR-1179, thus activating the high-mobility group box 1 (HMGB1) signaling pathway to regulate the tumor growth of PTC." (PMID 33150169, 2020). "Collectively, these data suggest that Arf1 ablation induces its anti-tumor effect through ATP and HMGB1." (PMID 31924786, 2020). "Tumor cytokines’ dynamics indicate that as the tumor grows, HMGB1, IFN-γ and μ1 (IL-6, IL-17, IL-21, IL-22) increase in density, but TGF-β and μ2 (IL-10, CCL20) stay relatively constant." (PMID 33291412, 2020). "The expression of HULC was downregulated in the HULC-depleted tumours, accompanied by an upregulated expression of miR-372-3p and downregulated HMGB1." (PMID 32188407, 2020). "The release of HMGB1 (high mobility group box 1) protein from cell nuclei was also triggered by mEHT 24 h post-treatment and then released and cleared from tumor cells after 48 h." (PMID 32872532, 2020). "GSDME-mediated pyroptosis promotes the development of CAC by releasing HMGB1, which induces tumor cell proliferation and PCNA expression through the ERK1/2 pathway." (PMID 33160389, 2020). "Experiments with animals demonstrated that the inhibition of HmgB1 interaction with this receptor suppresses tumor growth and spread metastasis." (PMID 33114717, 2020). "Anthracycline can induce a tumor-specific immune response through HMGB1 release in the late stage, and play a role in enhancing the antigen expression of dead tumor cells to DCs through the TLR4 receptor in ALL cells." (PMID 32660524, 2020).
tumor (continued). "TIM-3 binds to its ligands, including galectin-9, high mobility group box 1 (HMGB1), and carcinoembryonic antigen cell adhesion molecule 1 and plays a role in immune evasion of tumor cells by inactivating T cells." (PMID 32916853, 2020). "The binding of extracellular HMGB1 to TLR4 induces efficient cross-presentation of tumor antigens by DCs." (PMID 32178288, 2020). "HMGB1 release from dying tumor cells, which is required for the processing and cross-presentation of antigens, serves as another hallmark of ICD." (PMID 32144446, 2020). "In the hypoxic tumor center, HMGB1 was located in the cytoplasm of tumor cells, whereas in the normoxic tumor edge it was present in the nucleus of tumor cells." (PMID 32943604, 2020). "It was demonstrated that miR‐505 and HMGB1 were closely associated with TNM staging, tumor size, and distant metastasis." (PMID 32348630, 2020). "HMGB1 interaction with the RAGE receptor can thus mediate a significant level of cell proliferation and tumor development in the autophagy-deficient liver." (PMID 32382012, 2020). "These sHDLs displayed prolonged blood circulation and tumor-specific accumulation of DOX that enhanced the release of HMGB1 and promoted cell surface expression of CRT in both CT26 and MC38 tumor models." (PMID 32317755, 2020). "On the other hand, as a tumor-promoting factor, HMGB1 is released by tumor cells and can increase the recruitment of immunosuppressive cells, thereby promoting tumorigenesis, invasion and metastasis." (PMID 32551121, 2020). "Generally, positive expression of fibulin-3 was detected in the cytoplasm, while the expression of HMGB1 protein was commonly observed in the nuclear of tumor cell." (PMID 33230247, 2020). "miR-129-5p, a downstream target gene of lncRNA MALAT1, targeting regulates downstream transcription factor HMGB1 and participates in OS cell proliferation and tumor progression." (PMID 32953888, 2020). "Tumor cell-derived HMGB1 suppresses naturally acquired CD8+ T cell-dependent antitumor immunity by stimulating Tregs to produce IL-10, which is necessary for Treg-mediated immunosuppression." (PMID 32551121, 2020). "For instance, tumor activated PMNs, recruited through HMGB1 produced by UV-damaged epidermal keratinocytes, promote cancer cell transmigration and enhanced metastasis." (PMID 32133298, 2020). "While the expression of total HMGB1 was comparable in isolated tumors and cultured tumor cell lines, CD45 and dsHMGB1 were highly expressed only in isolated tumors." (PMID 32670275, 2020). "Contrary, in breast cancer, intracellular HMGB1 acts as an inhibitor of tumor progression while binding Rb (retinoblastoma) protein." (PMID 32684831, 2020). "PTX treatment increased HMGB1 expression in tumor tissues, and similar results were also found in the OXP-treated group." (PMID 32724476, 2020). "HMGB1 stimulates tumor antigen-presenting dendritic cells, which arise together with monocytes within the common myeloid progenitor lineage, to cause cytotoxic T-cell activation." (PMID 31893287, 2020). "In marked contrast, one study has shown that HMGB1 interacted with tumor‐infiltrating DCs to suppress nucleic acid‐mediated antitumor activity in mice with established tumors." (PMID 33179413, 2020). "These pro-inflammatory mechanisms of HMGB1-orchestrated tumorigenesis, as well as the prognostic potential of detection of elevated expression of this protein in the tumor microenvironment, represent the major thrusts of this review." (PMID 32664328, 2020). "Several studies have shown that HMGB1 can either promote or contrast tumor growth in both tumorigenesis and cancer therapy." (PMID 33584695, 2020). "Meanwhile, tumor cell-derived exosomal HMGB1 was also found to activate neutrophils through the TLR4/NF-κB pathway, which promotes its survival by increasing the autophagic response and polarizing TANs to a protumor type." (PMID 32849640, 2020).
tumor (continued). "During tumor development and therapy, pleiotropic HMGB1 mediates diverse biologic functions, promoting both cell survival and death by regulating unique signaling pathways." (PMID 33013860, 2020). "HMGB1–RAGE interaction at tumor cells acts through different molecular pathways, leading to tumor proliferation, migration, and invasion." (PMID 33117687, 2020). "HMGB1 promotes the expression of lymphotoxin α1β2 in tumor-infiltrating T cells, which can further lead to the recruitment of CD11b+F4/80+ macrophages to the tumor site." (PMID 32551121, 2020). "Although there have been strategies reported to enhance tumour cell death in an immunogenic way by increasing the amount of released HMGB1 into the TME, the fate of released HMGB1 has received limited attention." (PMID 33009382, 2020). "The C@HPOC supplied oxygen to the tumor and upon laser irradiation increased ROS, as well as promoted the release of HMGB1 and ATP and the cell surface expression of CRT." (PMID 32317755, 2020). "Among its multiple functions supporting tumor proliferation, HMGB1 improves chemotherapy resistance through the induction of autophagy in human myeloid leukemia cells." (PMID 32792960, 2020). "Taken together, these results exhibit the variety of HMGB1 SNPs in different cancers, consistent with the oncogenic and tumor-suppressing dual roles of HMGB1 during tumor development and therapy." (PMID 33023053, 2020). "Soluble RAGE (s-RAGE) is an endogenous cleaved soluble form of RAGE that blocks the HMGB1-RAGE signaling pathway in animal tumor models and has decoy receptor properties." (PMID 32660524, 2020). "Extracellular HMGB1 activates proinflammatory signals and supports tumorigenesis, thereby promoting inflammation, progression of the tumor, and formation of metastases." (PMID 32684831, 2020). "Extracellular HMGB1 has a paracrine role, promoting the processing and presentation of tumor antigens by dendritic cells." (PMID 32456685, 2020). "Overall, these results demonstrate that the redox state of HMGB1 is modulated locally during cancer cachexia progression and indicate that leukocytes act as transporters of dsHMGB1 isoform in the tumor microenvironment." (PMID 32670275, 2020). "The analysis of mice serum revealed that the CAP treatment induced a two-time increase in HMGB1 1 h after the second CAP exposure in the tumor-bearing mice." (PMID 32698492, 2020). "RAGE, which is absent in adult healthy muscle, is re‐expressed in atrophying myofibers via p38 MAPK under the action of proinflammatory cytokines and elevated serum levels of S100B and HMGB1, released from tumour cells." (PMID 32159297, 2020). "In part, HMGB1 enhances the suppressive activity of MDSCs by enhancing their capacity to produce IL-10 which, in turn, suppresses anti-tumour immunity and polarizes the activation of pro-tumour immune phenotype." (PMID 32931721, 2020). "Although we found that HMGB1 was increased expressed in bevacizumab resistance tumor in vivo, a link between HMGB1 and TLR4 still unproved." (PMID 33214550, 2020). "In this review, we detail the currently reported characteristics of MDSCs in tumor immune escape and the regulatory role of secreted HMGB1 in MDSC differentiation, proliferation, activity and survival." (PMID 32551121, 2020). "In this context, HMGB1 apparently induces tumor cell production of thymic stromal cell lymphopoietin (TSLP), an epithelial-derived cytokine that promotes T cell maturation via interaction with antigen-presenting cells." (PMID 32664328, 2020). "We propose, for the first time, that CD62Ldim neutrophils are significantly increased during the early stage of tumor progression and are regulated by HMGB1 secreted from the primary tumor." (PMID 32943604, 2020). "In the tumor micro-environment, HMGB1 maintains the survival of MDSCs through facilitating autophagy, which promotes the potency of MDSCs to restrain anti-tumor immunity and accelerate tumor progression." (PMID 33552058, 2020).
tumor (continued). "Parker and co-workers have shown that alarmin high mobility group box 1 (HMGB1) enhances immune suppression in tumour-bearing mice by facilitating the differentiation and suppressive activity of MDSCs." (PMID 32931721, 2020). "HMGB1 expression in primary tumors increased with tumor progression, and the concentration of HMGB1 in serum also increased over time." (PMID 32943604, 2020). "Tumor tissues formed by HMGB1 knockdown tumor cells exhibited a reduced proportion of CD62Ldim neutrophils and reduced lung metastasis of tumors, effectively extending the survival period of the mice." (PMID 32943604, 2020). "HMGB1 plays nuclear factor role or extracellular signaling molecule role during cell migration and tumor metastasis." (PMID 32489453, 2020). "Subsequently, ICD of the CT-26 tumor cells was analyzed by observing HMGB1 release into the culture medium." (PMID 33260446, 2020). "Collectively, the immunosuppressive effects of HMGB1 serve to inhibit the generation of de novo tumor-specific immunity, as well as suppress the maintenance of pre-existing anti-tumor responses." (PMID 33013860, 2020). "Accordingly, we identified circulating, infiltrating, and resident leukocytes as reservoirs and transporters of dsHMGB1 in tissue and tumor microenvironment, demonstrating that the redox state of HMGB1 is controlled at both tissue and cell levels." (PMID 32670275, 2020). "Based on the different DOX release rates from the DOX-PLGA7K NPs and DOX-PLGA12K NPs, the CT-26 tumor cells showed a different cytotoxicity and HMGB1 secretion." (PMID 33260446, 2020). "SNHG14 is a long noncoding RNA which in A549 cells suppresses the microRNA, miR-34a, a negative regulator of high mobility group box 1 (HMGB1) mRNA, whose increased expression can promote anti-tumor drug resistance." (PMID 33302475, 2020). "We demonstrate that S100B and HMGB1 are able to induce muscle atrophy per se at relatively high doses, behaving as cachexia‐inducing factors, and that S100B and HMGB1 are massively released from tumour masses." (PMID 32159297, 2020). "High expression of HMGB-1 in NSCLC, compared to normal lung tissues, has been associated with tumor cell proliferation, migration, and angiogenesis." (PMID 33167343, 2020). "Previous research suggested that tumor cells are the major contributors to HMGB1 secretion in the TME." (PMID 32551121, 2020). "They reported that preoperative chemoradiotherapy upregulates HMGB1 both within the tumour microenvironment and the serum of patients." (PMID 32246277, 2020). "The alarmin HMGB1 is released by most types of tumor cells and is detected in the serum of many cancer patients." (PMID 32551121, 2020). "ICD of tumour cells is characterized by inducing extracellular release of HMGB1 as “find me” signal and cell surface expression of calreticulin (CRT) as “eat me” signal." (PMID 33009382, 2020). "The effects of HMGB1 on T cell proliferation and phenotype are dependent on the source of HMGB1, resulting from tumor or myeloid cells, and the T cell activation status." (PMID 33013860, 2020). "This showed that the interaction of HMGB1 with RAGE was critical to maintain an inflamed tumor microenvironment and to tumor growth." (PMID 33256110, 2020). "Tim3 is expressed on tumor-infiltrating DCs and inhibits innate immunity by binding to its another ligand high mobility family protein 1(HMGB1) competitively with nucleic acids, thus leading to tumor immune escape." (PMID 33330064, 2020). "The major contribution of extracellular HMGB1 to invasiveness and tumor metastasis occurs via its interaction with RAGE; however, an intracellular role of HMGB1 in tumor progression has also been reported." (PMID 33256110, 2020). "In all, these data demonstrate that tumor-derived HMGB1-S100B/RAGE signaling adversely affects muscle mass as well as tumor biology, possibly also affecting inflammatory and immune events." (PMID 33291708, 2020).
tumor (continued). "Alarmins include ATP, proteins such as high mobility group box 1 (HMGB1), phosphatidylserine, etc. and are one of the causes of tumor-associated inflammation." (PMID 32290386, 2020). "These tumor cell preparations secreted significantly more HMGB1 than the untreated counterparts, and their lysates promoted the expression of maturation markers in cDC1s." (PMID 32178288, 2020). "At the same time, HMGB1 inhibits the antigen presentation function of dendritic cells and tumor-killing in CD8+ T cells, which also promotes the recruitment of M2 macrophages." (PMID 32943604, 2020). "Although there is increasing evidence of the impact of HMGB1 on tumor progression and metastasis, many contradictory findings have been reported." (PMID 32943604, 2020). "Although the data are preliminary, tumor cell-derived HMGB1 and TSLP seemingly act in concert with DCs in the TME to promote the maturation of Tregs, albeit by mechanisms that remain to be conclusively established." (PMID 32664328, 2020). "The concentration of HMGB1 in the tumor cell culture supernatant (TCCS) increased gradually with the prolongation of hypoxia." (PMID 32943604, 2020). "oAds kill infected tumor cells with features of necrosis/necroptosis, and autophagy accompanied by release of high mobility group box-1 (HMGB-1), calreticulin, extracellular ATP, and heat shock protein 70 (Hsp70)." (PMID 33202717, 2020). "In the 4T1 xenograft tumor model, LINCL significantly increased the cell surface expression of CRT, promoted HMGB1 release, and facilitated DC maturation in the tumor-draining lymph nodes to a greater extent than were realized in the laser-insensitive group." (PMID 32317755, 2020). "The tumor tissues showed a higher expression of fibulin-3 and HMGB1 than adjacent tissues (V = 1659.5 and 1706, respectively; P < 0.001)." (PMID 33230247, 2020). "By targeting HMGB1, miR-22 inhibits HMGB1-mediated autophagy in OS cells, thereby acting as a tumor suppressor." (PMID 32302291, 2020). "The results showed that the HMGB1 expression (cHMGB1) in the tumor cells (both B16 and CT26) infected with the NDV-MIP3α or NDV-WT and the release to the supernatants (sHMGB1) were almost the same." (PMID 32759233, 2020). "Because of its pivotal role in the progression of MM, HMGB1 is considered one of the most important potential targets for inhibiting tumor growth, metastasis, and drug resistance and optimizing current anti-MM treatment strategies." (PMID 32660524, 2020). "HMGB1 is overexpressed in different tumor types and has been proposed as a target for cancer therapy." (PMID 32792960, 2020). "Such a mechanism of tumor growth was also operative during exposure of cancer cell lines (Hepa 1–6, Huh 7) to hypoxia in vitro, and was attenuated by knockdown of either HMGB1 or TLR9." (PMID 32664328, 2020). "Migration to the TME can be mediated by eotaxins (eotaxin-1/CCL11, eotaxin-2/CCL24, eotaxin-3/CCL26) that bind the CCR3 receptor highly expressed on eosinophils and by alarmins (i.e., HMGB1 and IL-33) released from dying tumor cells." (PMID 33329534, 2020). "DAMPs from dying tumor cells, such as heat shock proteins or HMGB1, are able to trigger protective immune responses against the tumor growth via TLR signaling." (PMID 32788720, 2020). "When TIM-3 binds to HMGB1, the transport of nucleic acids into endosomes is blocked; thus, the pattern-recognition receptor-mediated innate immune responses against tumor-derived nucleic acids is suppressed." (PMID 33425759, 2020). "How does HMGB1 affect MDSCs in different tumor types or in different growth stages of the same tumor type?" (PMID 32551121, 2020). "The multiple effects of HMGB1 enable the tumor to rapidly establish collateral circulation after the original blood supply is interrupted by embolization, which leads to the tumor to regain some vessels after TACE." (PMID 33473353, 2020).